CCDC144A (coiled-coil domain containing 144A)
Description:
May play a role in preventing the formation of kidney stones through inhibition of calcium oxalate monohydrate (COM) crystallization, attenuating COM-induced apoptotic injury to renal epithelial cells. May exhibit antilithiatic (preventing the formation of kidney stones) activity through crystal binding, hindering the crystal attachment to renal epithelial cells, a pre-requisite to initiate inflammatory response.
Synonyms: KIAA0565; FLJ43983
Tractability: PROTAC: ubiquitination databases record sites on it.
Gene: Protein-coding gene on chromosome 17 (16,689,537 to 16,777,974, forward strand). Ensembl gene ENSG00000170160.
Subcellular location (Human Protein Atlas): Cytosol; Cell Junctions
Gene Ontology:
Molecular function: calcium oxalate binding
Genetic constraint (gnomAD): Loss-of-function variants: 37 observed, 85.46 expected, observed/expected ratio (o/e) 0.43, 90% interval 0.33 to 0.57. The synonymous counts are far from expectation, so gnomAD's model fits this gene poorly and the ratio says little. Missense variants: 563 observed, 998.14 expected, observed/expected ratio (o/e) 0.56, 90% interval 0.52 to 0.61. Synonymous variants: 217 observed, 341.88 expected, observed/expected ratio (o/e) 0.63, 90% interval 0.57 to 0.71.
Diseases named in the same sentence as CCDC144A in open-access papers:
CCDC144A is named in the same sentence as 4 diseases in open-access papers, as found by Europe PMC text mining. Sharing a sentence is not in itself a finding about the gene and the disease. The quoted sentences say what the papers report.
major depressive disorder (1 paper, 2024). An episode of depression lasting two or more weeks without an intervening episode of mania. "Finally, the variety of DEGs detected in the Major Depressive Disorder datasets was high, and only the gene CCDC144A (Coiled-Coil Domain Containing 144A) was dysregulated in more than one of the datasets analyzed." (PMID 39727940, 2024).
malignant tumors (1 paper, 2023). "The role of DLGAP2 and CCDC144A in malignant tumors is still unclear, but previous studies have suggested that TFAP2A can promote or inhibit cancer progression in tumors." (PMID 38125697, 2023).
CCDC144A also shares sentences with these, for which no sentence is quoted: breast carcinoma (1 paper); preeclampsia (1).